TRIM25 (tripartite motif containing 25)
Diseases named in the same sentence as TRIM25 in open-access papers (continued):
Sharing a sentence is not in itself a finding about the gene and the disease.
infection (continued). "In contrast, TRIM25 in VACV-Cop-infected cells was found in punctate structures as early as 1 hpi, with the number of these structures increasing over the course of infection." (PMID 40719442, 2025). "Higher-molecular weight, ubiquitylated TRIM25 species were evident as early as 1 h post-infection of HeLa cells with VACV-Cop, and they persisted throughout infection." (PMID 40719442, 2025). "Both poly(I:C) treatment and infection with an RNA virus trigger the co-condensation of TRIM25 and G3BP1, which dramatically increased the ubiquitination activity of TRIM25 toward substrates, many of which were localized in SGs." (PMID 38750080, 2024). "Next, we established HeLa stable cells expressing TRIM8, TRIM25, TRIM26, TRIM32, and TRIM33 to evaluate their effects on VEEV-TC83-GFP infection." (PMID 39527628, 2024). "We identified important genes DE in both our in vitro and in vivo infection models consistent with previous studies, namely, TLR3, IFIH1 (MDA5), SOCS1, OASL, DDX60, STAT1, MX1, CMPK2, LY96 (MD-2), STAT1, STAT2, TRIM25, IRF7, and IFIT5." (PMID 38675946, 2024). "It was chosen for several reasons: firstly, TRIM25 RNA-binding activity is upregulated upon infection with SINV and, secondly, that overexpression of TRIM25 potently reduces SINV infection." (PMID 39353916, 2024). "It is in the early stages of infection that ZAP acts to prevent the translation of alphaviral RNA by synergizing with the host E3 ubiquitin ligase, tripartite motif containing 25 (TRIM25)." (PMID 38045310, 2023). "Previous research indicated that TRIM25 is essential for the RIG-I-mediated production of IFNs and antiviral activity in response to infection with viral RNA." (PMID 37391858, 2023). "We found that overexpression of TRIM25 significantly reduced the level of HEP-Flury replication at 12 h and 24 h post infection (hpi)." (PMID 37628607, 2023). "We found that the expression of some Trim proteins was altered, especially Trim25, which was significantly changed after HEP-Flury infection." (PMID 37628607, 2023). "Taken together, our study provides support for the mechanism of action of TRIM25 against RABV, contributing to better understanding of the regulation mechanism of I-IFN on HEP-Flury infection." (PMID 37628607, 2023). "We recently reported that tripartite motif protein 25 (TRIM25), an important ISG, was highly upregulated in duck embryo hepatocyte cells (DEFs) after infection with duck viral hepatitis A virus type 1 (DHAV-1)." (PMID 37391858, 2023). "In the study, we found that duck TRIM25 can induce the production of IFN-β against double-stranded RNA virus stimuli and that the SPRY domain of duTRIM25 was critical for the infection." (PMID 36360326, 2022). "In contrast, we found six proteins altered by infection with CoV-2(B), among which five were downregulated (i.e., STAT1, HLA-E, TPR, TRIM25, and TRIM28)." (PMID 36175400, 2022). "This was the case for the type I IFN response, but also for RIPK1, STAT1, DDX58, ISG15, TRIM25, and MYD88, involved in TNF-, TLR-, RLR-, and NFκB signaling, 48 h after MOPV infection." (PMID 35337059, 2022). "Crucially, after both 3p-hpRNA transfection and infection with PR8 R38K41A IAV at an MOI of 15 the levels of IRF-3 phosphorylation were similar in WT and TRIM25 KD cells." (PMID 35736141, 2022). "Taken together, our findings suggest that duck TRIM25 can induce the production of IFN-β against double-stranded RNA virus stimuli and that the SPRY domain of duTRIM25 was critical for the infection." (PMID 36360326, 2022). "(B) CoIP and immunoblot analyses of RIG1 KO HEK293T cells transfected with HA-Ev or HA-RTN3 together with GFP-tagged TRIM25 (GFP-TRIM25) or GFP-Ev for the indicated groups for 24 hr and followed by infection with VSV (MOI = 1) for 8 hr." (PMID 34313226, 2021). "Here we see that RNF135 is upregulated by infection with either BC500 or VN1203 in all tissues, while TRIM25 is upregulated in both lung and spleen during VN1203 infection." (PMID 34804075, 2021).
infection (continued). "TRIM25 was upregulated in BHK-21 cells, duck embryo fibroblasts, and 293T cellsupon DTMUV infection." (PMID 34595229, 2021). "When silencing TRIM25 by siRNA transfection, the relative amount of DTMUV mRNA increased significantly in two TRIM25 siRNAs transfected DEFs after DTMUV infection." (PMID 34595229, 2021). "Our results showed that TRIM25 expression was increased 1.6-fold, and the RIG-I-like receptor signaling pathway was significantly enriched during infection." (PMID 31865850, 2020). "When the siRNAs HRSV-F, TRIM25/HRSV-F, or the combination of TRIM25 plus HRSV-F were transfected before infection, the levels of IL6, CCL5, and IFN-β mRNAs increased significantly at 24 hpi." (PMID 31035368, 2019). "TRIM25 and RIG-I downregulation was also measured at 24 h post-transfection (before infection) in the case of cells transfected with TRIM25, RIG-I, TRIM25/HRSV-F, or RIG-I/HRSV-N siRNAs." (PMID 31035368, 2019). "The putative role of the OTU in infection remains paradoxical, as ubiquitination of RIG-I by tripartite motif-containing protein 25 (TRIM25) activates it, whereas ISGylation of RIG-I negatively regulates RIG-I activation by competing with ubiquitination sites." (PMID 27110812, 2016). "Using Huh7.25.CD81 cells that ectopically express TRIM25, we observed that HCV triggers IFNβ induction as early as 6 hrs after infection, demonstrating that the entry of the virus into the cell rapidly generates enough viral structured RNAs to activate RIG-I." (PMID 20485506, 2010). "Altogether, the combined effect of TRIM25 expression and PKR depletion resulted in 58% of inhibition of HCV virus yields at 24 hrs and 56% at 48 hrs post-infection." (PMID 20485506, 2010). "Taken together, these results suggest that TRIM25 is ubiquitylated in response to infection of HeLa cells with many, but not all, Orthopoxviruses." (PMID 40719442, 2025). "Proteomic data from PBMCs collected at 0, 3, and 6 dpi confirmed that both strains induced activation of intracellular sensors (RIG-I, OAS1, and TRIM25) and transcriptional factors such as EIF2AK2, although activation was consistently stronger during MA08 infection." (PMID 39992151, 2025). "PHEV significantly upregulated ISG15 expression (>1.5 log2FC) at all three time points, and it appears ISG15 does interact with HERC5, IFIT1, PKR, TRIM25, STAT1, and USP18, as their expression was also enhanced (>1.0 log2FC) at various timepoints during ALI-PRECs infection." (PMID 38932231, 2024). "Knockdown of Trim25 increased HEP-Flury P protein levels, RNA genome levels, virus titers and N protein levels detected by immunofluorescence at 12 and 24 h after HEP-Flury infection." (PMID 37628607, 2023). "In contrast, TRIM25 overexpression reduced HEP-Flury P protein levels, RNA genome levels, viral titers, and immunofluorescence detection levels of N protein at 12 and 24 h after HEP-Flury infection." (PMID 37628607, 2023). "During infection with the hepatitis B virus, IL-27 was found to be critical for the IFN-I-mediated production of TRIM25; specifically, the knockout of IL27R1 or treatment with the IL-27-neutralizing antibody significantly inhibited TRIM25 expression." (PMID 37391858, 2023). "Furthermore, we also found that COX-5B was significantly up-regulated, while TRIM25, TRIM21, TRIM27 and TRIM26 were significantly down-regulated in the PAMs with a PRRSV-ADE infection in this study." (PMID 36680075, 2022). "Especially, many mutations occur in the effector domain (ED) of NS1 that interacts with a number of host factors, including retinoic acid-inducible gene 1 (RIG-I), tripartite motif containing 25 (TRIM25), and phosphoinositide 3-kinase (PI3K), during the infection cycle." (PMID 36182933, 2022). "Furthermore, the expression of several innate immune response regulators (COX-5B, MMP-9, TRIM21, TRIM25 and TRIM26) in the PAMs were also regulated differently during the PRRSV-ADE infection." (PMID 36680075, 2022).
infection (continued). "Notably, multiple antiviral proteins were also dramatically decreased in PAMs during the PRRSV-ADE infection, including ISG15, ISG20, IFIT1 (ISG56), IFIT2 (ISG54), IFIT3 (ISG60), IFIT5 (ISG58), OAS1, Mx1, RSAD2, TRIM22, TRIM25 and TRIM34, except for TRIM52." (PMID 36680075, 2022). "Overexpression of TRIM25-WT (solid light blue line) dramatically represses SINV replication by 7–15 fold at earlier timepoints (6–12 hours post infection (h.p.i.)) to 43–52 fold at later timepoints (24–40 h.p.i.)compared to TRIM25 KO 293T cell lines (dotted lines)." (PMID 36067236, 2022). "In HEK293T cells, the expression of endogenous human TRIM25 was not elevated by infection with the two NS1-mutant viruses either (lower)." (PMID 34867921, 2021). "The expression of endogenous TRIM25 in PAMs was not significantly changed upon infection with Hf09 and the two viruses harboring the NS1 C-terminal deletion (upper)." (PMID 34867921, 2021). "(G) IP and immunoblot analyses of HEK293T cells transfected with HA-Ev or increasing amounts of HA-RTN3 (+, ++) together with Flag-RIG-I and GFP-tagged TRIM25 (GFP-TRIM25) or GFP-Ev in the indicated groups for 24 hr and followed by infection with VSV (MOI = 1) for 8 hr." (PMID 34313226, 2021). "Indeed, it has been shown that H3N2 and H2N2 IAV strains infections lead to a high IRF3 and IFNβ activation, despite a proper interaction between NS1 and TRIM25." (PMID 34835115, 2021). "It binds to viral RNA, TRIM25, RIG-1, and promotes viral replication and reduces interferon response, but upon phosphorylation during the later stage of infection, its binding to viral RNA, TRIM25, and RIG-1 reduces, thereby negatively affecting viral replication and immune response." (PMID 33396899, 2020). "Characterization of the immune response induced by different pathogens in murine alveolar macrophages infected at high MOI, showed a higher induction of TRIM25 expression in delNS1 infected cells compared with PR8 infection (data not shown)." (PMID 32188146, 2020). "TRIM25 expression was slightly increased by the infection in the absence of EPZ (although not statistically significant)." (PMID 32188146, 2020). "Furthermore, most of the immune-related genes, particularly TLR7, TRAF3, Mx, TRIM25, CD4, and CD8α, increased in response to GPV and H9N2 infection." (PMID 27916934, 2016). "QRT-PCR revealed that gosling TRIM25 expression levels were significantly downregulated in the trachea of H9N2-infected birds 1 day after infection and in the blood, brain, and small intestines 3 days after infection." (PMID 27995135, 2016). "In order to assess whether UBE2L6 and TRIM25 are induced as rapidly as ISG15 at the protein level, we monitored their expression by immunoblot at 3 hr post infection." (PMID 26259872, 2015). "Indeed, ectopic expression of a TRIM25 P358L construct was as efficient as a TRIM25wt construct to increase IFN induction in the Huh7.25.CD81 cells, after infection with Sendai virus (SeV)." (PMID 22022264, 2011). "Conversely, TRIM25-m9 remained diffuse after infection and did not accumulate in these foci." (PMID 39353916, 2024). "As a control we could show that neither overexpression of TRIM25, nor ZAP, affected total cell-associated trVLP genomes 3 hours post-infection." (PMID 35533151, 2022). "Of note previous reports showed that Favipriavir added only prior to infection allows for full IAV RNA synthesis inhibition, however, our experiments necessitated prior accumulation of IAV RNAs before the transcription inhibition to observe the effects of TRIM25 on the stability of IAV RNAs." (PMID 35736141, 2022). "The other flavivirus capsid proteins also interacted with TRIM25, suggesting that these viral proteins may attenuate antiviral signaling pathways at very early stages of infection, potentially even before nonstructural proteins are produced." (PMID 35632712, 2022).
infection (continued). "The TRIM25-R54P specific hits may have weaker, more transient, or infection-specific interactions not easily detected by the conventional co-IP/MS approach." (PMID 36067236, 2022). "Considering that the RTN3 overexpression leads to its aggregation in the ER and may cause nonspecific interactions (such as structural enfolding), we used GFP-TRIM25 to pull down endogenous RTN3 and confirmed its interaction with TRIM25 and that this interaction was strengthened by VSV infection." (PMID 34313226, 2021). "The N protein of SARS-CoV-2 promoting TRIM25 interacts with G3BP2 (GTPase-activating protein SH3 domain–binding protein 2), inhibiting type I interferon production in the process of infection without involving the ubiquitination of TRIM25." (PMID 40723303, 2025). "It has been reported that the expression of TRIM25 in DHAV-1-infected duck embryo hepatocyte cells (DEFs) was upregulated; however, its specific role during infection and mechanism of upregulation have not been elucidated yet." (PMID 37391858, 2023). "In salmonids, TRIM25, MAVS, MDA5, and RIG-I were induced following infection with an alphavirus although the signaling pathways were not addressed directly." (PMID 28829373, 2017). "Inhibition of virus yields did not increase later in infection (36% at 48 hrs post-infection), in agreement with the block on IFN induction downstream of TRIM25 imposed by the NS3/4A-mediated cleavage of MAVS." (PMID 20485506, 2010).
tumor (62 papers, 2007 to 2026). "Differential gene expression analysis was performed to identify pathways associated with TRIM25 expression in both low and high TRIM25-expressing tumour groups." (PMID 41689405, 2026). "High TRIM25 expression was significantly associated with MCPyV positivity in both patient tumours (p = .004) and cell lines (p = .016), and TRIM25 and MCPyV mRNA levels correlated positively in tumours (r = 0.264, p = .013)." (PMID 41689405, 2026). "Elevated TRIM25 levels are associated with poor prognosis and enhanced tumor growth both in vitro and in vivo." (PMID 41511341, 2025). "As a member of the E3 ubiquitin ligase family, TRIM25 has been reported to be associated with tumor prognosis." (PMID 38926803, 2024). "TRIM25 has been implicated in the increased proliferation of many cancer cell types, and knockdown of TRIM25 often results in attenuated tumor growth." (PMID 32826889, 2020). "Although accumulating evidence suggests TRIM25 roles in key pathways implicated in tumorigenesis, the exact mechanism by which TRIM25 modulates tumor progression remains unclear." (PMID 32826889, 2020). "Additionally, TRIM25 may play a pathogenic role in MCPyV-positive tumours, warranting further investigation to elucidate its mechanistic involvement in MCC tumourigenesis." (PMID 41689405, 2026). "Therefore, TRIM-associated protein expressions were analyzed based on PCa transcriptome data, and the expression levels of several TRIM-associated proteins (above the dashed line), including TRIM25 (*), in tumor tissues were significantly higher than those in the normal tissues." (PMID 36012594, 2022). "Functional studies in GBM cell lines, patient-derived cultures, and tumor models demonstrate that TRIM25-mediated HIF-1α stabilization promotes tumor proliferation, invasion, and angiogenic potential." (PMID 42020378, 2026). "Here, we identify TRIM25 as a key driver of tumor progression and chemoresistance by promoting the destabilization of AGO2." (PMID 42062253, 2026). "Functionally, TRIM25 promotes tumor cell survival by reducing the sensitivity of HCC cells to ferroptosis." (PMID 41993211, 2026). "After data normalization, the Kruskal-Wallis H test was applied to assess TRIM25 expression differences across tumor stages." (PMID 41993211, 2026). "Conversely, the authors of the study observed that treatment of tumor cells with the antibacterial compound nitroxoline by counteracting TRIM25-mediated PTEN ubiquitination was able to restore cell death sensitivity of NSCLC to cisplatin." (PMID 39851496, 2025). "TRIM25, a potential E3 ubiquitin ligase, promotes the ubiquitination and degradation of its substrates, playing vital roles in tumor cell proliferation, apoptosis, immune regulation, and antiviral responses." (PMID 41315221, 2025). "The recovery of BRD7 expression reversed the inhibitory effects of TRIM25 knockdown on the proliferation, tumor growth, and paclitaxel resistance of BC cells in vitro and in vivo." (PMID 41315221, 2025). "Data from our own laboratory revealed that in addition to controlling the transcriptome of tumor cells, TRIM25 affects post-transcriptional regulation of the pro-apoptotic caspase-2 and caspase-7 via different mechanisms." (PMID 39851496, 2025). "The ubiquitination activity of TRIM25 enhances tumor cell survival and modifies regulatory proteins in innate immunity, e.g., the activation of RIG-I and TRAF proteins." (PMID 40431746, 2025). "For that reason, TRIM25 is increasingly recognized as a valid tumor marker and promising target of novel antitumor therapy." (PMID 39851496, 2025). "For example, in non-small cell lung cancer (NSCLC), TRIM25 mediates the K63-linked ubiquitination of PTEN at the K266 site, and promotes the proliferation of NSCLC cells and tumor growth by activating AKT/mTOR signaling pathway." (PMID 41315221, 2025).